TUG1 (taurine up-regulated 1)
Diseases named in the same sentence as TUG1 in open-access papers (continued):
Sharing a sentence is not in itself a finding about the gene and the disease.
glioblastoma (16 papers, 2017 to 2025). The most malignant astrocytic tumor (WHO grade IV). "Currently, a phase I trial is underway for oligonucleotide therapy targeting the long non-coding RNA TUG1 in recurrent glioblastoma, which provides a direct reference for targeting LINC02167 in therapy." (PMID 40234937, 2025). "The lncRNA TUG1 is upregulated in glioblastoma CSCs and promotes their self-renewal by sponging miR-145 and recruiting polycomb repressive complex 2 (PRC2) to repress genes required for differentiation." (PMID 31197235, 2020). "Authors of these TUG1 studies focused on different biological features of glioblastoma (angiogenesis versus proliferation/apoptosis)." (PMID 30217088, 2018). "These cellular processes were mediated by TUG1 interaction with miR-299, which was downregulated in glioblastoma." (PMID 29147648, 2017). "Overexpression of TUG1 was involved in glioblastoma angiogenesis by modulation of endothelial cell proliferation, migration, and tube formation." (PMID 29147648, 2017). "Among these innumerable examples, the TUG1 lncRNA sponges many miRNAs in multiple regulatory axes and cancers: the TUG1/miR-299/VEGF-A axis increases angiogenesis in glioblastoma, while the TUG1/mir-34a-5p/VEGF-A axis is thought to contribute to hypervascularity in hepatoblastoma." (PMID 37444543, 2023). "In glioblastoma, intravenous treatment with ASOs targeting TUG1, in conjunction with a sophisticated drug delivery system, induces GSC differentiation and efficiently inhibits GSC growth in vivo, indicating that TUG1 may be a potent therapeutic approach to eradicate the GSC population." (PMID 39015773, 2024). "Because LN229 has a high level of DNA methylation in the promoter of MGMT (82.7% by pyrosequencing analysis), we examined the effect of TUG1 ASO and TMZ in another glioblastoma cell line U251MG, which has a lower level (23.2%) of DNA methylation in the MGMT promoter." (PMID 37607907, 2023). "Note that co-treatment of TUG1 ASO and three DNA-damaging agents with distinct modes-of-action (cisplatin, Temozolomide (TMZ) and CPT) showed synergistic induction of apoptosis and suppression of the growth of cancer cells including glioblastoma." (PMID 37607907, 2023). "TUG1 colocalizes with pRPA32 at R-loop and DHX9 in the glioblastoma cell line LN229." (PMID 37607907, 2023). "Although further investigation is required, TUG1 ASO may be a powerful strategy for targeting this dire tumor entity, particularly because of its synergetic effects with TMZ or Irinotecan, an analog of CPT also clinically used for glioblastoma treatment." (PMID 37607907, 2023).
pancreatic cancer (16 papers, 2017 to 2024). "Inhibition of H6PD expression levels produces suppressive effects on pancreatic cancer cells H6PD overexpression locally offset the effects of TUG1 deficiency on retinoblastoma proliferation and apoptosis." (PMID 37601754, 2023). "For example, Qin and Zhao demonstrated that lncRNA TUG1 can promote the malignant progression of pancreatic cancer via the EMT pathway." (PMID 36105715, 2022). "We depicted a TUG1/miR-144-3p/COL10A1 axis to investigate the regulatory mechanism of COL10A1 in pancreatic cancer progression." (PMID 36105715, 2022). "Among them, TUG1 has been reported to promote proliferation and migration of pancreatic cancer cells through the regulation of EMT." (PMID 36071042, 2022). "The TUG1/miR-144-3p/COL10A1 axis was identified as the most likely upstream noncoding RNA pathway for COL10A1 in pancreatic cancer." (PMID 36105715, 2022). "TUG1 knockout blocked cell cycle, accelerated apoptosis and inhibitted the proliferation of pancreatic cancer cells." (PMID 34039257, 2021). "lncRNA TUG1/miR-29c axis promoted the growth and migration of pancreatic cancer cells in vivo and in vitro." (PMID 34039257, 2021). "lncRNA TUG1/miRNA-299-3p axis promoted the malignant progression of pancreatic cancer by inhibiting the Notch1 pathway." (PMID 34039257, 2021). "Upregulation of lncRNA TUG1 regulates cell cycle, proliferation, and apoptosis of pancreatic cancer." (PMID 33865422, 2021). "An oncogene in pancreatic cancer known as TUG1 put together miRNA-299-3p brought a significant approach in treating pancreatic cancer." (PMID 32854710, 2020). "Taurine-upregulated gene 1 (TUG1) was reported as miR-299-3p sponge and inhibition of TUG1/miR-299-3p expression dampened pancreatic cancer progression via suppressing the Notch1 signaling pathway." (PMID 32549762, 2020). "In pancreatic cancer, upregulated lncRNA TUG1 binds to and recruits EZH2 to the promoter regions of RND3 and MT2A." (PMID 33050646, 2020). "lncRNA TUG1 induced cycle arrest in pancreatic cancer cells and promoted apoptosis." (PMID 34039257, 2021). "Thus, TUG1/EZH2 triggers anti-apoptosis during pancreatic cancer by silencing its tumor-suppressive target genes." (PMID 33050646, 2020). "In addition, several studies have shown the relevance of TUG1 to pancreatic cancer." (PMID 36105715, 2022). "For instance, TUG1 within CAF-derived EVs boosts glycolysis in liver cancer, while SNHG3 enhances this process in breast cancer, and NNT-AS1 does so in pancreatic cancer." (PMID 39717771, 2024). "The lncRNA taurine upregulated gene 1 (TUG1) cooperates with EZH2 to down-regulate miRNA-382 and aid in sponging, leading to EMT induction and pancreatic cancer invasion." (PMID 35236381, 2022). "The lncRNA TUG1/enhancer of zeste homolog 2 (EZH2) axis promoted the proliferation, migration, and EMT phenotype of pancreatic cancer cells by sponging miR-382." (PMID 34039257, 2021). "Only 10 (SCAMP1, EMG1, HCP5, TUG1, MAL2, H19, LINC00511, RP11-311C24.1, RP11-400F19.6 and CTC-459F4.3) out of 90 lncRNAs were significantly upregulated in pancreatic cancer samples when compared with normal controls." (PMID 31061236, 2019). "This is exemplified in various cancers: TUG1 in liver cancer; MEG3 and HOTAIRM1 in lung cancer; LINC00355 in bladder cancer; TUC338 in laryngeal squamous cell carcinoma; FTX in oral squamous cell carcinoma; and NNT-AS1 in pancreatic cancer." (PMID 39717771, 2024).
hepatoblastoma (15 papers, 2016 to 2025). Hepatoblastoma (HB) is a malignant hepatic tumor and is the most common pediatric liver cancer. "Western blots and enzyme-linked immunosorbent assay (ELISA) experiments showed that TUG1 knockdown significantly decreased VEGFA levels in hepatoblastoma tissue and blood." (PMID 27362796, 2016). "Meanwhile, the LNCRNA TUG1 was increased in hepatoblastoma, stimulating the downstream signaling pathway of JAK2/STAT3 and promoting angiogenesis in hepatoblastoma cells." (PMID 36104680, 2022). "LncRNA TUG1 can also suppress tumor growth and angiogenesis in hepatoblastoma and is upregulated in hepatoblastoma." (PMID 35592755, 2022). "Its knockdown has similar effects to CRNDE and is involved in abnormal vascular proliferation in hepatoblastoma through the TUG1/miR‐34a‐5p/VEGFA axis." (PMID 35592755, 2022). "TUG1 was highly expressed in hepatoblastoma, which is a common malignant hepatic tumour in children, and it was also associated with an increased risk of tumour metastasis." (PMID 34968230, 2019). "TUG1 is suggested as a potential target to combat the abnormal angiogenesis and improve hepatoblastoma treatment." (PMID 34968230, 2019). "We also show that TUG1 is a promising therapeutic target for aggressive, recurrent, or metastatic hepatoblastoma." (PMID 28178668, 2017). "Based on in vivo and in vitro evidence, we show that TUG1 upregulation contributes to unusual hypervascularity for hepatoblastoma progression." (PMID 27362796, 2016). "miR-34a-5p was found to be downregulated in hepatoblastoma tissues, showing an opposite expression trend compared with TUG1 expression pattern." (PMID 27362796, 2016). "TUG1 was significantly upregulated in hepatoblastoma tissues compared with the matched normal tissues." (PMID 27362796, 2016). "In this study, we aim to elucidate the biological and clinical significance of TUG1 upregulation in hepatoblastoma." (PMID 27362796, 2016). "Collectively, these results suggest that TUG1 is a potential regulator involved in the tumorigenesis of hepatoblastoma." (PMID 27362796, 2016). "To reveal the role of TUG1 expression change in hepatoblastoma in vivo, we used a mouse hepatoblastoma xenograft model to determine the effect of TUG1 knockdown on tumor growth and angiogenesis." (PMID 27362796, 2016). "Overall, our findings indicate that TUG1 upregulation contributes to unusual hypervascularity of hepatoblastoma." (PMID 27362796, 2016). "To reveal the functional significance of TUG1 alteration in hepatoblastoma in vitro, we first designed three different TUG1 siRNAs." (PMID 27362796, 2016). "We show that TUG1 is significantly upregulated in human hepatoblastoma specimens and metastatic hepatoblastoma cell lines." (PMID 27362796, 2016). "Tumor size was significantly reduced in the TUG1 knockdown group 2 weeks after hepatoblastoma inoculation." (PMID 27362796, 2016). "In conclusion, we show that TUG1 level is significantly upregulated in liver samples from patients with hepatoblastoma and in the metastatic hepatoblastoma cell lines." (PMID 27362796, 2016). "TUG1 knockdown inhibits tumor growth and angiogenesis in vivo, and decreases hepatoblastoma cell viability, proliferation, migration, and invasion in vitro." (PMID 27362796, 2016). "Thus, it is required to consider TUG1 tissue specificity when TUG1 is intervened for treating hepatoblastoma." (PMID 27362796, 2016). "We then determined whether TUG1-miR-34a-5p interaction is involved in regulating hepatoblastoma cell function." (PMID 27362796, 2016). "TUG1 upregulation contributes to the hypervascularity of hepatoblastoma via VEGFA induction." (PMID 27362796, 2016). "TUG1 is a promising therapeutic target for aggressive, recurrent, or metastatic hepatoblastoma." (PMID 27362796, 2016).
hepatoblastoma (continued). "Once lncRNA-TUG1 is significantly upregulated during hepatoblastoma progression, TUG1 upregulation could alleviate miR-34a-5p repressive effect, resulting in a significant increase in the expression of VEGFA, a target gene of miR-34a-5p." (PMID 27362796, 2016). "Therefore, lncRNA TUG1 might be responsible for the hypervascularity, which is characteristic for hepatoblastoma." (PMID 32992718, 2020). "Thus, the TUG1/miR-34a-5p/VEGF-A axis contributes to unusual hypervascularity in hepatoblastoma." (PMID 31404273, 2019). "TUG1/miR-34a-5p/VEGFA network may become a candidate target for hepatoblastoma therapy." (PMID 27362796, 2016). "In hepatoblastoma (HB), another type of liver cancer, the highly expressed lncRNAs CRNDE and TUG1 were shown to bind miR-203 and miR-34-5p, respectively." (PMID 32992718, 2020). "A recent study reported that TUG1/miR-34a-5p/VEGFA network was involved in regulating hypervascularity and hepatoblastoma progression." (PMID 29228631, 2017). "TUG1/miR-34a-5p/VEGFA network is involved in regulating hypervascularity and hepatoblastoma progression." (PMID 27362796, 2016). "TUG1, miR-34a-5p, and VEGFA constitutes to a regulatory network, and participates in regulating hepatoblastoma cell function, tumor progression, and tumor angiogenesis." (PMID 27362796, 2016). "Similarly, research has identified that lncRNAs TUG1, HOXA-AS2, OIP5-AS1, ZFAS1, SNHG9, NBR2 and MIR205HG are significantly upregulated in HB cells and enhance cell proliferation, migration or invasion in hepatoblastoma." (PMID 38390281, 2024).
liver cancer (14 papers, 2017 to 2025). An epithelial or non-epithelial malignant neoplasm that arises from the liver. "In the context of ICC, an aggressive type of liver cancer, It has been shown that taurine upregulates gene 1 (TUG1), a lncRNA, contributes to increased glutamine metabolism via suppressing miR‐145." (PMID 40567251, 2025). "The down‐regulation of TUG1 in HCC cells can inhibit both PD‐L1 and CD47, which indicates that TUG1 is a potential biomarker and immunotherapeutic target for liver cancer, thereby providing new ideas for enhancing antitumor immunity." (PMID 38981064, 2024). "In a parallel mechanism, TUG1, derived from CAFs, enters liver cancer cells and engages in the TUG1/miR-524-5p/SIX1 pathway, facilitating SIX1-driven glycolysis through the “ceRNA” mechanism." (PMID 39717771, 2024). "In summary, our study demonstrates that TUG1 and PD-L1 are highly expressed in liver cancer tissues and have potential as biomarkers and therapeutic targets." (PMID 37813900, 2023). "Research confirmed that high TUG1 expression and high levels of infiltration of pro-tumor immunocytes in liver cancer tissue leading to the malignant progression." (PMID 37813900, 2023). "Recent studies have found that lncRNA TUG1 is upregulated in a variety of cancers, including B‐cell malignancy, oesophageal squamous cell carcinoma, ovarian cancer, liver cancer and osteosarcoma." (PMID 35421276, 2022). "Downregulation of TUG1 can significantly inhibit the migration, invasion, and proliferation of liver cancer cells." (PMID 34659578, 2021). "TUG1 is expected to be a biomarker and therapeutic target for the diagnosis and prognosis of liver cancer." (PMID 34659578, 2021). "The results of qRT-PCR showed that the expression of TUG1 in liver cancer tissues and cells was significantly higher than that in adjacent tissues and normal hepatocytes." (PMID 34659578, 2021). "We found that the expression of TUG1 in liver cancer cells (HCC-LM3) was significantly higher than that in the normal cells and hepatocytes (HL-77O2), which is consistent with the previously reported results." (PMID 34659578, 2021). "Next, we checked the expression of miR-29a in liver cancer specimens by qRT-PCR and constructed a scatter plot with TUG1 expression." (PMID 34659578, 2021). "To study the interaction between TUG1 and miR-29a in liver cancer, we first transfected TUG1 siRNA and miR-29a inhibitor into HCC-LM3 and MHCC-97H cells and subsequently detected the expression of miR-29a mRNA." (PMID 34659578, 2021). "In the present study, we show that upregulation of miR-132 inhibits the proliferation of liver cancer cells, and we identified TUG1 as a ceRNA that interferes with the binding of miR-132 to Shh, affecting the Hh pathway and the progression of HCC." (PMID 29029483, 2017). "To further confirm the mechanism of TUG1 in regulating antitumor immunity, we downregulated TUG1 in human liver cancer HepG2 cells and found that both miR‐340 and miR‐141 were upregulated in TUG1‐downregulated cells, while the expressions of PD‐L1 and CD47 decreased." (PMID 38981064, 2024). "In addition, we downregulated TUG1 in another human liver cancer LM3 cells and found that both miR‐340 and miR‐141 were upregulated in TUG1‐downregulated cells, while the expressions of PD‐L1 and CD47 decreased." (PMID 38981064, 2024). "In this study, we demonstrated that lncRNA TUG1 upregulation was mediated by METTL3‐mediated m6A modification and examined the underlying mechanism of how TUG1 in liver cancer cells regulates the antitumor response of CD8+ T cells and phagocytosis of macrophages." (PMID 38981064, 2024). "However, it is unclear how the combination of TUG1 and miRNA affects the progression of liver cancer." (PMID 34659578, 2021). "The expression of TUG1 in liver cancer tissue was negatively correlated with miR-29a." (PMID 34659578, 2021). "Moreover, we found that TUG1 was highly expressed in our liver cancer samples using qRT-PCR, whereas miR-29a was lowly expressed in HCC." (PMID 34659578, 2021).
liver cancer (continued). "Taurine Up-Regulated 1 (TUG1) has been proved to be a proto-oncogene, and the up-regulated TUG1 expression in the HCC group is correlated with the Barcelona Clinic Liver Cancer (BCLC) staging and tumor size compared with the control group." (PMID 34758879, 2021). "The objective of this study was to investigate the regulatory relationship between TUG1, miR-29a, and IFITM3 in human liver cancer." (PMID 34659578, 2021). "Of the large number of lncRNAs identified so far, some (e.g., TUG1 and HOTAIR) have been shown to play very important roles in multiple aspects of liver cancer such as tumourigenesis, tumour recurrence and drug resistance." (PMID 29061150, 2017). "TUG1, as an lncRNA, plays an important role in several tumors; however, its specific mechanism of action in liver cancer has not been studied." (PMID 34659578, 2021). "Previous studies have reported that TUG1 is highly expressed in liver cancer and is related to the subsequent negative effects of HCC." (PMID 34659578, 2021). "Therefore, we aimed to explore the relationship between lncRNA TUG1, miR‐1‐3p and IGF1 and their influence mechanism on the proliferation and apoptosis of liver cells to provide new insights into the prevention and treatment of liver cancer." (PMID 35421276, 2022).
esophageal cancer (13 papers, 2015 to 2024). A primary or metastatic malignant neoplasm involving the esophagus. "Dysregulated lncRNAs, such as UCA1, HOTAIR, and TUG1, have been proposed as prognostic biomarkers for esophageal cancer." (PMID 35619131, 2022). "Long non-coding RNA TUG1 has also been found to be abundantly expressed in TE-1-derived DDP-resistant esophageal cancer cells TE-1/DDP." (PMID 34881242, 2021). "In esophageal cancer however, the role of Tug1 seems to be quite different.Tug1 is found to be over expressed in cancer tissue with expression being correlatedwith tumor stage." (PMID 27508057, 2016). "More recently, aberration lncRNA expressions in esophageal cancer were reported, such as up-regulation of HOTAIR, taurine-upregulated gene 1 (TUG1), PlncRNA1, POU3f3, FOXCUT, HNF1A-AS1, ANRIL and signature identification (lncRNAs ENST00000435885.1, XLOC_013014 and ENST00000547963.1)." (PMID 25885227, 2015).
lymph node metastasis (13 papers, 2014 to 2022). "Previous studies have shown that TUG1 is significantly associated with histological grade, tumor stage, lymph node metastasis, and distant metastasis of ccRCC." (PMID 36528763, 2022). "A higher TUG1 level was associated with lymph node metastasis, pathological differentiation, and clinical stage, and the high expression of TUG1 was associated with the poor prognosis of patients with PC." (PMID 30595764, 2018). "High TUG1 expression was significantly associated with tumor stage (P < 0.001), intrahepatic metastasis (P = 0.001), lymph node metastasis (P < 0.001), and perineural invasion (P = 0.029)." (PMID 29371936, 2017). "Subsequently, we investigated the prognostic value of TUG1 with lymph node metastasis and distant metastasis." (PMID 33747256, 2021). "This meta-analysis collected all eligible studies about TUG1, SPRY4-IT1, and HULC and explored the relationship between lncRNAs expression and lymph node metastasis (LNM) or overall survival (OS)." (PMID 29145271, 2017). "Univariate analysis identified four prognostic factors: lymph node metastasis (N0, N1 or above), TNM stage (I/II, III/IV), distant metastasis (M0, M1) and TUG1 expression." (PMID 26913601, 2016). "Elevated TUG1 expression was correlated with larger tumor size, advanced international federation of gynecology and obstetrics (FIGO) stage, poor differentiation, and lymph node metastasis." (PMID 28088836, 2017). "Multivariate analysis further revealed that TUG1 expression could be regarded as an independent predictor for overall survival in patients with GC (P=0.003), as well as TNM stage (P=0.019) and lymph node metastasis (P=0.001)." (PMID 26913601, 2016). "Therefore, a systematic review and meta-analysis has been carried out to explore the expression of these 3 well-known lncRNAs (TUG1, SPRY4-IT1, and HULC) and lymph node metastasis and the overall survival to prove these 3 lncRNAS might serve as biomarkers in cancer prognosis and diagnosis." (PMID 29145271, 2017).